EGFR (epidermal growth factor receptor)
Diseases named in the same sentence as EGFR in open-access papers (continued):
Sharing a sentence is not in itself a finding about the gene and the disease.
cancer (continued). "Here, we leverage base editing and prime editing technologies to establish complementary MAVEs, which we apply to EGFR in human cancer and noncancer cells." (PMID 39533106, 2025). "Therefore, these compounds modulate key signaling pathways such as EGFR/Ras/Raf/MEK/ERK, ROS, MEK, and PI3K/AKT, thereby exerting control over cancer cell proliferation, survival, and metastasis." (PMID 40490812, 2025). "However, a better understanding of the biology of the EGFR signaling pathway in CRC, coupled with the development of liquid biopsy methodologies to study cancer evolution in real time, fostered the clinical refinement of anti‐EGFR treatment in CRC." (PMID 39470386, 2025). "•Some cancer stem markers are CD44, HLA-I, pan-cytokeratin, and EGFR." (PMID 40738059, 2025). "As biomarkers of cancer, EGF and EGFR have significant roles." (PMID 39996991, 2025). "In cancers without EGFR amplification, high HRAS expression indicated aggressive disease and unfavorable prognosis." (PMID 41463200, 2025). "In vitro studies showed that they could be selectively internalized into EGFR‐positive 4T1 and HT29 cancer cells." (PMID 39717005, 2025). "Although immune checkpoint inhibitors (ICIs) have revolutionized cancer treatment, advantages for advanced NSCLC, in terms of OS, have been reported for EGFR wild-type tumors, but not for EGFR-mutated lung tumors." (PMID 40243603, 2025). "Antibody-drug conjugates (ADCs), such as human epidermal growth factor receptor 2 (HER-2), nectin cell adhesion molecule 4 (Nectin-4), and epidermal growth factor receptor (EGFR)-targeted ADC drugs, have been explored recently and have been shown to be effective in several human cancers." (PMID 41425706, 2025). "Considering previous reports on the relationship between MMPs and the efficacy of EGFR inhibitors, we believe that the correlation between MMP-28 and EGFR inhibitors in PDAC may be applicable to other cancers as well." (PMID 39994761, 2025). "Indeed, the novel platinum-EGFR inhibitor complex KP2749 exhibited quenched fluorescent properties, which allowed us to study the release of KP2187 by confocal microscopy in living cancer cells over time." (PMID 39801772, 2025). "A number of cellular processes that contribute to the growth and advancement of cancer cells can be inhibited by luteolin through the reduction in the activity of certain receptor tyrosine kinases (RTKs), including IGFR, EGFR, and ERs, as well as their downstream effector molecules." (PMID 40728967, 2025). "The overexpression of the epidermal growth factor receptor (EGFR) and the human epidermal growth factor receptor 2 (HER2) protein kinases leads to the stimulation of VEGF production and promotes angiogenesis in most human cancers." (PMID 40283934, 2025). "EGFR and VEGFR-2 have been identified as viable therapeutic targets in cancer treatment." (PMID 40395767, 2025). "ZNRF3/RNF43 loss-mediated EGFR stabilization represents a novel mechanism of EGFR upregulation, explaining the elevated EGFR protein levels observed in many human cancers without EGFR gene amplification or overexpression." (PMID 38260423, 2024). "Through its interaction with EGFR on the cell surface, ANXA2 regulates the activation of EGFR and the downstream PI3K-AKT signaling pathway, which is important for malignant phenotypes, such as cancer cell proliferation and migration." (PMID 39333871, 2024). "Clinical characteristics and outcomes and treatment patterns were assessed for 13 084 patients with NSQ cancer who had known EGFR and ALK status (75.4%; mean [SD] 62.2 [10.5] years; 6552 males [50.1%]) and all 4751 patients with SQ cancer (mean [SD] age, 67.1 [8.6] years; 4427 males [93.2%])." (PMID 38334998, 2024).
cancer (continued). "The activation of the EGFR signaling pathway enhances IGF-1 secretion and directly drives M2 macrophage polarization, resulting in an immunosuppressor effect and promoting the development of cancer." (PMID 39619695, 2024). "Compounds 6 (MS39) and 10 (MS154) potently induced the degradation of EGFR mutant but not EGFR wild type (wt) in cancer cell lines." (PMID 39456995, 2024). "Other therapeutic strategies, including EGFR inhibitors, have not achieved the same degree of success seen in other cancers, partly due to the blood–brain barrier and intrinsic resistance." (PMID 38727302, 2024). "Therefore, despite its lack of a cytoplasmic signaling domain, CD24 has the capacity to recruit crucial signaling molecules, such as EGFR, ERK, and AKT, and promote tumorigenicity in both cancer cells and CSCs." (PMID 38881902, 2024). "In order to overcome this resistance, a therapeutic armamentarium consisting of ICIs and anti-cancer agents with immunomodulatory effects (e.g., anti-VEGFR or anti-EGFR) has been proposed to enhance the immunogenic profile of these lesions and make checkpoint blockade more effective." (PMID 38893120, 2024). "Cancer stem cells (CSCs) in these tumors exhibit characteristics that are similar to those of normal stem cells and express several markers, including CD133+, CD15, CD49f+, CD36+, A2B5+, CD44+, L1CAM+, and the epidermal growth factor receptor (EGFR+)." (PMID 39451383, 2024). "EGFR, phosphatidylinositol 3‐kinase (PI3K)/AKT, and RAS/MAPK signaling pathways are important regulators of metabolism, including lipid metabolism (such as that involving FASN), in cancer." (PMID 38874588, 2024). "Additionally, cancer cells driven by a CCDC6-RET, a distinct fusion shown to form condensates, also showed EGFR suppression that was restored upon drug treatment." (PMID 39488530, 2024). "EGFRV948R transfection retained STAT3 phosphorylation in EGFR−/−, TMEM25−/− TNBC cells, strongly suggesting that EGFR can phosphorylate STAT3 in the monomeric form in the absence of TMEM25 and thereby relays sustainable proliferative signals to cancer cells to provide the growth advantage." (PMID 38532948, 2024). "Unlike traditional chemotherapy, TKIs specifically target cancer cells by inhibiting autophosphorylation at the EGFR, reducing toxicity and improving patient outcomes." (PMID 39337496, 2024). "Several studies have shown that EGFR and PDK1 interact reciprocally, promoting cancer development." (PMID 38689087, 2024). "Despite evidence of therapeutic efficacy in other cancers, anti-EGFR antibodies have shown limited activity in TNBCs that are not exclusively dependent on EGFR signaling for survival." (PMID 38772416, 2024). "The results confirmed the strong anti-cancer activity of cyclin-dependent kinase 12 and 13 (CDK12/13) inhibitors and the synergistic effect of THZ531 and pathway inhibitors (EGFR, RPTOR, ATRIP) regulated by cancer-related genes on the activity of HGSOC organoids." (PMID 38989138, 2024). "Moreover, numerous oncogenic drivers (ALK, BRAF, EGFR, MET, NRG1, NTRK1/2/3, RET, and ROS1) involved in sole reciprocal fusions were found in those cancers." (PMID 39254060, 2024). "Beyond traditional chemotherapy, cetuximab, an anti-EGFR monoclonal antibody, counteracts the Warburg effect by inhibiting HIF-1α regulated lactate dehydrogenase A (LDH-A), thus, disrupting the metabolic reprogramming that promotes cancer cell survival." (PMID 39169426, 2024). "In addition, NK cell–mediated ADCC is also exploited in the treatment of various cancers, and is enhanced in patients with HNSCC after treatment with cetuximab, the only clinically approved EGFR-targeted therapy." (PMID 38147007, 2024).
cancer (continued). "This analysis indicates that SY may inhibit FGFR2, EGFR, CAH2, KEAP1, and GSK3β, which are involved in various cellular processes related to cancer development and oxidative stress response." (PMID 38431714, 2024). "Multiple EGFR-targeting therapeutics including afatinib, neratinib, and cetuximab are FDA approved for the treatment of other cancers and could be quickly applied to DSRCT in the clinic, making EGFR an exciting therapeutic target." (PMID 39139449, 2024). "The anticancer ability of FGFC1 was investigated in NSCLS and EGFR-mutant NSCLC cells and reported that FGFC1 inhibited cell growth and cancer cell migration by down-regulating the NF-kB signaling pathway via signaling protein expressions such as IL-6, TNF-α, p-IκB, and p-p65." (PMID 39359937, 2024). "As STAP-2 is important for EGFR-mediated signaling, including the phosphorylation of EGFR, ERK, and STAT3 and proliferation of some human cancer-cell lines, we tested whether 2D5 suppresses these functions in a previous study." (PMID 38745775, 2024). "Cancer cells use non-mutational adaptations to resist a wide variety of single drugs or drug combinations, including inhibitors targeting BRAF, MEK, EGFR, and KRAS." (PMID 38668053, 2024). "According to KEGG analysis, CFF-1 could have anti-cancer effects against PCa by regulating cancer cell proliferation and survival through PI3K-Akt, HIF-1, TNF, EGFR-TKI resistance and PD-1 checkpoint signaling pathways." (PMID 38484140, 2024). "Curcumin treatment of CRC cells also downregulates miR-27a, miR-20a, and miR-17-5p to promote transcription factors ZBTB10 and ZBTB4, which inhibit several downstream target genes, including EGFR, c-MET, cyclin D1, and NFκB, resulting in cancer cell growth arrest and apoptosis induction." (PMID 38542474, 2024). "Additionally, expressions of EGFR, NECTIN4, TROP2, HER2, and HER3, the molecules which are considered to serve as therapeutic targets of cancers, were assessed." (PMID 39582977, 2024). "A study reported a trispecific NKCE platform, including α-CD16, α-4-1BB, α-EGFR and epirubicin (EPI), which facilitated the recruitment and activation of NK cells, which can ultimately promote NK cell recruitment and activation to eradicate these cancer cells." (PMID 39310113, 2024). "This superior performance may result from the use of PIC that target delivers BPD to EGFR-positive cancer cells, as well as the synergistic interaction between PDT and PARP inhibitors, leading to more effective cancer cell killing." (PMID 38321470, 2024). "Due to the big role EGFR plays in GBM proliferation and growth, and its very common overexpression and amplification in large amounts of patients, it is a frequent target for cancer therapies, especially for modern tyrosine kinase inhibitors." (PMID 39329751, 2024). "Moreover, an NP study of Yinchen Wuling San, a complex medical prescription comprising six medicinal plants used for cancer treatment, revealed that the genes TNF, AKT1, and EGFR are targeted by the bioactive compounds of Yinchen Wuling San against HNSCC." (PMID 39035991, 2024). "Finally, in CRC several TAAs target of autoantibodies have been widely explored in clinical trials as cancer vaccines as CEA, and MAGE, together with other pan-explored TAAs in different cancers as MUC1, EGFR, or Survivin." (PMID 39234247, 2024). "Like EGFR, increased IQGAP1 expression has also been found in a variety of cancers." (PMID 39357822, 2024). "EGFR, a member of the ErbB receptor family, orchestrates extracellular signals, such as EGF, directing cellular signaling cascades to promote cell proliferation, division, mitosis, and cancer development." (PMID 38817007, 2024). "In an in vitro coculture model consisting of healthy donor T and NK cells, EGFR-positive cancer cells, and ADCC (antibody-dependent cellular cytotoxicity)-inducing anti-EGFR-antibody Cetuximab, we studied different antitumoral effector functions in the presence of acellular ascitic fluid." (PMID 38646521, 2024).
cancer (continued). "In the field of oncology, currently approved ADCs target specific proteins overexpressed by cancer cells, such as HER2, trophoblast cell surface antigen 2 (Trop2), Nectin‐4, and EGFR in solid tumors, and CD19, CD22, CD33, CD30, and CD79b in hematologic malignancies." (PMID 39070179, 2024). "As a number of cancers overexpress both HER2 and EGFR (i.e. gastric, ovarian, breast), our results have potential to be translated into a wide range of solid tumors and PET imaging has potential to be used to identify which patients would be susceptible to dual HER2/EGFR combination therapies." (PMID 38355949, 2024). "Dual targeting of EGFR and HER2 is a valid anti-cancer approach for treating solid tumors." (PMID 39434991, 2024). "It is known that inhibition of EGFR and HER2 activation significantly affects redox regulation mechanisms in cancer cells and may lead to mitochondrial dysfunction." (PMID 39403185, 2024). "As EGFR-ERK signaling upregulates ZEB1, PRMT1-mediated EGFR upregulation may also contribute to ZEB1 upregulation and ZEB1-mediated cancer stem cell regulation." (PMID 39201539, 2024). "In addition to this mechanism, Anexelekto (AXL) has been found to mediate drug resistance in many cancers, while it is also involved in TKI resistance in EGFR-mutant NSCLC, probably by sharing the same signaling pathway with EGFR." (PMID 39336976, 2024). "In patients with EGFR mutations, and without either KRAS or EGFR mutations, cancer stage was only predictive of OS but not RFS." (PMID 39385301, 2024). "However, this needs to be further investigated as the role of TEM8 in cancer progression is still been elucidated, as well as its effects in other well-known pathways such as TGF-beta, EGFR, MAPK and Wnt-beta catenin." (PMID 39917181, 2024). "RAC2 also showed upregulation of proliferative pathways, including signalling by NTRK2/TRKB, characterised by overexpression of the PIK3CA gene, and signalling by ERBB2 in cancer, as reflected by elevated serum concentrations of SHC1, ERBB4, EGFR and ERBB2, compared with RAC3." (PMID 39401856, 2024). "Immunohistochemical results showed that anti-CK (+), anti-P40 (+), anti-CK5/6 (+), anti-Ki67 (+, hot spot area 80%) and anti-EGFR (++++) in cancer cells were high positive and anti-EBER (-) was negative." (PMID 39076983, 2024). "The activation of EGFR in turn phosphorylates/activates its downstream signaling molecules Akt, ERK‐1/2, JNK, and p38 which contribute to the tumorigenesis and metastasis of cancer cells." (PMID 38522013, 2024). "Additionally, various small molecule inhibitors targeting EGFR and/or ERBB2 have been approved for treatment of cancers such as NSCLC." (PMID 38713378, 2024). "GFB is a first-generation tyrosine kinase inhibitor (TKI), reversibly inhibiting EGFR autophosphorylation and downstream mitogen-activated protein kinase/phosphatidylinositol 3-kinase (MAPK/PI3K) signaling in EGFR-overexpressing cancers (breast, lung, colon, brain)." (PMID 39339166, 2024). "Nevertheless, the differential expression of EGFR and VEGFc, in addition to MMP9 and CXCL5, differentially packaging into IRF5-low versus IRF5-high EVs across two cancer types provide insight into the mechanisms by which IRF5 contributes to protection from PMN formation." (PMID 38969706, 2024). "Besides, we demonstrated that HLA-LOH was another major influential factor that impair the efficacy of neoadjuvant immunochemotherapy in EGFR-mutant NSCLC, which has also been illustrated in multiple cancer subtypes treated with immunotherapy." (PMID 38897205, 2024).
cancer (continued). "In the context of cancer, the extracellular domain of MUC1 is cleaved and released into systemic circulation wherein it appears to contribute to several intercellular signaling networks via RTK, EGFR and Akt interactions." (PMID 39020428, 2024). "Lapatinib is a well-tolerated oral EGFR and HER2 inhibitor in cancer patients." (PMID 38414024, 2024). "The targets EGFR and AKT1 are proteins that promote cancer occurrence." (PMID 39598341, 2024). "Therefore, EGFR and VEGFR-2 kinases are recognised targets in cancer therapy, with many FDA-approved inhibitors for clinical usage in solid tumors overexpressing EGFR and/or VEGFR-212,13." (PMID 39443462, 2024). "Dysregulation of RTKs, such as EGFR, VEGFR, HER2 or ROR, could lead to various diseases, particularly cancers." (PMID 39551787, 2024). "Silodosin was able to promote pro-apoptotic activity in cancer cells and inhibit aggressive cancer growth, leading to significant anti-NSCLC activity that could be attributed to its allosteric EGFR inhibition." (PMID 41451023, 2024). "Targeting intact EGFR and PKM2 complexes in the nucleus may overcome resistance to cancer radiotherapy." (PMID 39404930, 2024). "AXL receptor overexpression and interaction with non-TAM RTKs like MET and EGFR diversify signaling in cancer cells." (PMID 38474160, 2024). "Additionally, other hotspots have also been studied in specific cancers, such as IDH1 and IDH2 in gliomas, EGFR in the lung, and BRAF in skin cancer." (PMID 38473427, 2024). "Furthermore, EGFR also contributes to the TME in EC by increasing cellular reliance on the extracellular matrix (ECM), thereby promoting cancer cell growth and survival within the ECM." (PMID 39415846, 2024). "Furthermore, studies have shown that the combination of EGFR and HER3 antagonism with AKT inhibition enhances the anti-cancer effects." (PMID 38183074, 2024). "Moreover, not only has EGFR been reported to modulate autophagy in NSCLC and other mammalian cancer cell lines, but all its downstream signaling pathways have also been demonstrated to regulate autophagy." (PMID 38764025, 2024). "EGFR signaling pathways activate lipogenesis through PI3K/AKT and MAPK pathways, leading to increased de novo lipid synthesis and alterations in lipid metabolism that support cancer cell growth and proliferation." (PMID 39456607, 2024). "It is approved for the treatment of various cancers, including epidermal growth factor receptor (EGFR) negative, anaplastic lymphoma kinase (ALK) rearrangement negative non-small cell lung cancer (NSCLC)." (PMID 39512511, 2024). "Hence, the simultaneous suppression of both EGFR and VEGFR-2 holds great potential as a cancer treatment strategy due to its synergistic impact." (PMID 39569013, 2024). "The Epidermal Growth Factor Receptor(EGFR), Vascular Endothelial Growth Factor Receptor 2 (VEGFR2), EGFRKinase and PI3K α structures have been identified as targetsknown to be effective against cancer cells." (PMID 38911768, 2024). "Over the past decade, tyrosine kinase inhibitors (TKIs) have made significant advances in the treatment of cancer, especially NSCLC.EGFR-TKI, as a potent agent for the treatment of over-activation of EGFR signalling, has been developed for multiple generations with remarkable efficacy." (PMID 39391313, 2024). "Previous research has shown that the EGFR inhibitor, erlotinib, can have either positive or negative effects on overall survival for various types of cancers." (PMID 39057088, 2024). "We identified EGFR as a direct target of ISO, suggesting that ISO could be utilized against EGFR-related pathologies, including cancer." (PMID 38203840, 2024). "Furthermore, ORes regulates the EGFR/PI3K/AKT/GPX4 axis, targeting both ferroptosis and key cancer-related pathways, which distinguishes it from other ferroptosis inducers." (PMID 39881871, 2024).